HUWE1 (HECT, UBA and WWE domain containing E3 ubiquitin protein ligase 1)
Diseases named in the same sentence as HUWE1 in open-access papers (continued):
Sharing a sentence is not in itself a finding about the gene and the disease.
infection (7 papers, 2014 to 2025). The state of being infected such as from the introduction of a foreign agent such as serum, vaccine, antigenic substance or organism. "Our results showed that the silencing of Huwe1 significantly reduced viral titers in the cell culture supernatants at 48 h post-infection with SARS-CoV-2." (PMID 39034993, 2024). "The mRNA levels of Ubb and Huwe1 reached the peak at 16 h after infection and were approximately 40 and 12 times higher than the untreated cells, respectively." (PMID 39114448, 2024). "To rule out that the effects oncolony formation were due to variations in infection efficiency, we generated Ls174T cells thatexpress one of the two shRNAs targeting HUWE1 in a doxycycline-inducible manner (Fig1B)." (PMID 25253726, 2014). "We observed an increase in both Huwe1 protein and mRNA expression at 24 h post-infection." (PMID 39034993, 2024). "In addition to mediating inflammasome activation and NF-κB signaling, HUWE1 was also identified by ISGs affinity proteomics to interact with ISG proteins, suggesting that HUWE1 might play essential roles in the ISG network upon infection and stress stimulation." (PMID 35937685, 2022). "The results showed that at both mRNA and protein levels, HUWE1 and TRAF6 were decreased during the infection." (PMID 35107378, 2022). "Additionally, HUWE1 and UBE2I gene expression levels were evaluated during infection, showing a decrease in expression when miR-215 mimic was overexpressed." (PMID 39943201, 2025). "This study only focused on the role of Huwe1 and Miz1 in the immune response to SARS-CoV-2 infection, and future studies may need to investigate their potential roles in other aspects of the infection, such as viral replication and pathogenesis." (PMID 39034993, 2024). "In addition, we found that apoptosis and ROS levels were upregulated when HUWE1 and TRAF6 were silenced during WSSV infection, suggesting the regulation of HUWE1 and TARF6 in apoptosis and ROS production during the infection." (PMID 35107378, 2022).
neurodevelopmental disorder (7 papers, 2017 to 2025). A behavioral and cognitive disorder with onset during the developmental period that involves impaired or aberrant development of intellectual, motor, or social functions. "The first genetic links between human HUWE1 and neurodevelopmental disorders emerged with the discovery that X-chromosome microduplications that lead to copy number variations (CNV) in HUWE1 are associated with non-syndromic, X-linked ID." (PMID 32336296, 2020). "In summary, a compelling body of human genetic studies and work using both mammalian and invertebrate model systems support several overarching concepts regarding HUWE1 and neurodevelopmental disorders." (PMID 32336296, 2020). "Over the past decade, HUWE1 has emerged as a relevant player in several neurodevelopmental disorders with the most prominent links to ID." (PMID 32336296, 2020). "Finally, we hope that continued human genetic and clinical studies will allow for more comprehensive, precise molecular genetic classification of HUWE1 neurodevelopmental disorders." (PMID 32336296, 2020). "Importantly, other ubiquitin ligase signaling hubs associated with childhood neurodevelopmental disorders, such as RPM-1 (MYCBP2) and EEL-1 (HUWE1), also utilize both ubiquitin ligase activity and ligase-independent mechanisms to shape neuron development and function 51,52." (PMID 40766417, 2025). "Extensive human genetic studies have provided compelling evidence implicating Huwe1 in multiple neurodevelopmental disorders, including both non-syndromic and syndromic forms of X-linked intellectual disability (ID)." (PMID 32336296, 2020).
adenocarcinoma (1 paper, 2017). A common cancer characterized by the presence of malignant glandular cells. "Four top performing EV-associated proteins that distinguished adenocarcinoma cases from controls, SRGN, TPM3, THBS1 and HUWE1, yielded a combined area under the receiver operating characteristic curve (AUC) of 0.90 (95% CI = 0.76-1)." (PMID 29221141, 2017).
colorectal (1 paper, 2017). "The mutual exclusivity of HUWE1 mutation and MYC genomic amplification we observe in human CRC strongly implicates them as critical mediators of colorectal tumourigenic." (PMID 28003334, 2017).
infectious disease (1 paper, 2022). A disorder directly resulting from the presence and activity of a microbial, viral, or parasitic agent in humans. "HUWE1 is considered a potential candidate contributor to X chromosome- and sex-linked susceptibility to infectious diseases." (PMID 35937685, 2022). "Recently, we defined HUWE1 as a master regulator of inflammasome activation and recognized its novel roles in the fields of inflammatory responses and infectious diseases." (PMID 35937685, 2022).
HUWE1 also shares sentences with these, for which no sentence is quoted: neurological diseases (2 papers); stomach adenocarcinoma (2); 3-M syndrome (1); acromelic dysplasia (1); acute kidney injury (1); B-cell neoplasm (1); blood cancer (1); brain cancer (1); breast tumour (1); Cerebellofaciodental Syndrome (1); cerebral cavernous malformation (1); ciliopathies (1); colon adenocarcinoma (1); developmental delay (1); Floating-Harbor syndrome (1); fragile X syndrome (1); Growth delay (1); head and neck squamous cell carcinoma (1); Immune Thrombocytopenic Purpura (1); injury (1); intestinal cancer (1); iron overload (1); liposarcoma (1); lymphoproliferative disorders (1); microcephaly (1); Mowat-Wilson syndrome (1); oxidative stress (1); Parkinson disease (1); prostate tumor (1); psychiatric diseases (1).
A further 8 diseases each share a sentence with HUWE1 in 1 paper.